FOLR2 (folate receptor beta)
Description:
Binds to folate and reduced folic acid derivatives and mediates delivery of 5-methyltetrahydrofolate and folate analogs into the interior of cells. Has high affinity for folate and folic acid analogs at neutral pH. Exposure to slightly acidic pH after receptor endocytosis triggers a conformation change that strongly reduces its affinity for folates and mediates their release.
Synonyms: FR-beta; FBP; FRβ; BETA-HFR; FBP/PL-1; FR-P3; FRbeta
Tractability: Small molecule: a structure with a bound ligand is known; a high-quality ligand is known. Antibody: UniProt places it where antibodies can reach, with high confidence; its Gene Ontology location is reachable by antibodies, with high confidence; UniProt predicts a signal peptide or a membrane-spanning region. PROTAC: a small molecule that binds it is known.
Target class: Membrane receptor
Gene: Protein-coding gene on chromosome 11 (72,216,601 to 72,221,950, forward strand). Ensembl gene ENSG00000165457.
Subcellular location: Cell membrane; Secreted
Pathways (Reactome):
Metabolism: Metabolism of folate and pterines
Metabolism of proteins: Post-translational modification: synthesis of GPI-anchored proteins
Gene Ontology:
Molecular function: folic acid binding; folic acid receptor activity; signaling receptor activity
Biological process: folic acid transport; monocyte chemotaxis; positive regulation of cell population proliferation; folic acid metabolic process; inflammatory response; cellular response to folic acid
Cellular component: cell surface; external side of plasma membrane; extracellular region; plasma membrane
Genetic constraint (gnomAD): Loss-of-function variants: 14 observed, 22.95 expected, observed/expected ratio (o/e) 0.61, 90% interval 0.4 to 0.95. The upper end of that interval is the gene's LOEUF score, 0.95, which puts it in group 4 of 6, group 1 being the genes least tolerant of losing a copy. Missense variants: 269 observed, 337.81 expected, observed/expected ratio (o/e) 0.8, 90% interval 0.72 to 0.88. Synonymous variants: 114 observed, 119.52 expected, observed/expected ratio (o/e) 0.95, 90% interval 0.82 to 1.11.
Homologues: Orthologues: chimpanzee FOLR2 (99% identical), macaque FOLR2 (96% identical), rat Folr2 (78% identical), mouse Folr2 (77% identical), pig FOLR2 (73% identical), zebrafish folr (49% identical), tropical clawed frog folr1 (47% identical). Paralogues in human: FOLR3 (78% identical), FOLR1 (73% identical), IZUMO1R (53% identical), RTBDN (15% identical).
Diseases named in the same sentence as FOLR2 in open-access papers:
FOLR2 is named in the same sentence as 96 diseases in open-access papers, as found by Europe PMC text mining. Sharing a sentence is not in itself a finding about the gene and the disease. The quoted sentences say what the papers report.
breast cancer (27 papers, 2015 to 2025). A primary or metastatic malignant neoplasm involving the breast. "In contrast, FOLR2+ TAMs of resident origin in human breast cancer are associated with favorable prognosis." (PMID 39516356, 2024). "Recent research reported a notable association between the abundance of FOLR2+ macrophages and improved prognostic outcomes in individuals diagnosed with breast cancer." (PMID 39170612, 2024). "In human breast cancer, tissue-resident FOLR2+ macrophages instead of M1 or M2 are proved to associate with CD8+ T-cell infiltration and better prognosis." (PMID 36814925, 2023). "The results showed that increased density of FOLR2+ macrophages was associated with favorable survival in breast cancer patients." (PMID 36172359, 2022). "Folate receptor beta 2 (FOLR2) is one of the prognostic genes associated with the breast cancer tumour microenvironment, and patients with high FLOR2 expression in lung adenocarcinoma have longer overall survival." (PMID 36248799, 2022). "Collectively, these studies demonstrate that macrophages expressing LYVE‐1 and associated markers (PDPN, TIM4, STAB1, and FOLR2) may have key roles in the context of breast cancer." (PMID 38426622, 2024). "Exogenous overexpression of carbonyl reductase has been observed to promote necrosis, inflammatory cell infiltration, and apoptotic phagocytosis in ovarian cancer in vivo, and FOLR2+ macrophages have been reported to associate with CD8+ T cell infiltration in human breast cancer." (PMID 37345658, 2023). "Folr2 expression is associated with protumor macrophages that exhibit an anti-inflammatory and immunosuppressive microenvironment in several cancers; however, in some indications (e.g., breast cancer), it has been associated with CD8+ T cell infiltration and better patient survival." (PMID 39255000, 2024). "A study in breast cancer found that FOLR2+ TAMs localized around the blood vessels in the tumor stroma, where they interact with CD8+ T cells." (PMID 40376263, 2025). "In breast cancer, FOLR2+ macrophages interact with CD8+ T cells, effectively activating them, and the density of FOLR2+ macrophages is strongly associated with patient survival." (PMID 41502512, 2025). "The density of FOLR2+ macrophages in tumors has been correlated with survival in breast cancer and HCC patients; therefore, the significant role we observed for Macro_FOLR2 + APOE+, and its interaction with T cells, is notable." (PMID 39034339, 2024). "Surprisingly, they found that FOLR2+ TAMs in breast cancer were MHCII-positive and expressed the gene signatures of both M1 and M2 simultaneously." (PMID 38068740, 2023). "A recent study of primary breast cancer tumors found that FOLR2+ tissue-resident macrophages are present in the tumor stroma, as opposed to TREM2+ macrophages that concentrate in tumor nests and margins." (PMID 37756565, 2023). "Studies have shown that the density of FOLR2+ macrophages in breast cancer is positively correlated with better patient survival." (PMID 38313432, 2023). "They found that a subset of FOLR2+ TAMs correlates with increased survival in patients with breast cancer." (PMID 36814925, 2023). "In fact, FOLR2 exhibits the highest level of correlation with MAF expression in breast carcinoma, a finding that agrees with the considerable decrease in FOLR2 expression that is seen upon MAF knockdown in human macrophages." (PMID 32532019, 2020). "Furthermore, in human breast cancer, FOLR2+ mammary resident macrophages in tumors, which are localized in perivascular areas in the tumor stroma, can efficiently prime effector CD8+ T cells and are correlated with patient survival." (PMID 40083710, 2025). "Specifically, we characterized tissue-specific macrophages present in breast cancer, denoted as FOLR2+ macrophages, hepatocellular carcinoma tissue-resident macrophages (Kupffer cells), and tissue-resident macrophages within lung cancer recognized as alveolar tissue-resident macrophages." (PMID 38648200, 2024).
breast cancer (continued). "In addition, FOLR2 + LYVE‐1 + TIM4+ macrophages have been found near blood vessels within human mammary tumors directly interacting with CD8+ T cells, resulting in a correlation between FOLR2+ macrophage count and patient survival." (PMID 38426622, 2024). "Thus, in human lung adenocarcinoma, single-cell transcriptome profiling suggested that FOLR2+ TAMs, as has been shown for breast cancer, also originate from tissue-resident (in this case, alveolar) macrophages." (PMID 39516356, 2024). "Further studies are needed to determine whether FOLR2 may be a druggable target for breast cancer patients." (PMID 38426622, 2024). "Additionally, in breast cancer primary tumors, FOLR2+ tissue-resident macrophages are positioned in the perivascular areas of the tumor stroma, where they interact with CD8+ T cells, and their density in tumors is positively associated with improved patient survival rates." (PMID 38229178, 2024). "TR FOLR2+ macrophages have been also identified in breast cancer (BC) lesions and in healthy mammary tissues; they were associated with high CD8+ T cell infiltration and better prognosis." (PMID 37342322, 2023). "have revealed a correlation between the density of FOLR2+ macrophages and tumor-infiltrating CD8+ T lymphocytes in breast cancer." (PMID 36172359, 2022). "In contrast to breast cancers, the survival data from the Human Protein Atlas and TCGA-COAD cohort showed that FOLR2 mainly indicated an unfavorable prognosis in colorectal cancer, implying its pro-tumor immunological function in colorectal tumors." (PMID 36172359, 2022).
rheumatoid arthritis (25 papers, 2011 to 2026). A chronic, systemic autoimmune disorder characterized by inflammation in the synovial membranes and articular surfaces. "Folate receptor beta (FR-β) has been used as a clinical marker and target in multiple inflammatory diseases, including osteoarthritis (OA) and rheumatoid arthritis (RA)." (PMID 35255727, 2022). "Next, we address the macrophage-restricted expression of FOLR2 in a pathology where macrophages preferentially exhibit a pro-inflammatory polarization, rheumatoid arthritis (RA)." (PMID 32532019, 2020). "First, we undertook to examine whether the folate receptor beta (FR-β) positive subpopulation of macrophages, which marks the inflammatory subset in animal models of rheumatoid arthritis, might constitute the prominent population of macrophages in inflamed lesions in humans." (PMID 31174578, 2019).
ovarian carcinoma (18 papers, 2015 to 2025). A malignant neoplasm originating from the surface ovarian epithelium. "FOLR2 exhibits high expression levels in tumor-associated macrophages (TAMs) of ovarian cancer and can be selectively depleted by G5-MTXNps." (PMID 37351109, 2023). "The folate receptor beta (FRβ) is specifically overexpressed on M2-polarized TAMs in various epithelial malignancies, including ovarian cancer, making it a promising immunotherapeutic target for modulating the tumor microenvironment." (PMID 40963633, 2025). "An alternate strategy to deplete TAMs is to exploit elevated expression levels of folate receptor-2 (FOLR2) that has been found in human and murine ovarian cancer TAMs, and use G-5 methotrexate nanoparticles to target these TAMs." (PMID 30274280, 2018). "In addition, our findings showing a correlation between high FOLR2 gene expression and worse PFS only in later stages of ovarian cancer further supports this notion." (PMID 33563975, 2021).
lung carcinoma (10 papers, 2018 to 2024). "The FOLR2 gene that encodes folate receptor 2 is overexpressed in M2-polarized TAMs in lung cancer." (PMID 37532692, 2023). "The Macro-1 cluster was transcriptionally similar to tissue-resident macrophages as reported in primary ccRCC, breast and lung cancers, and expressed markers such as SEPP1, FOLR2, CCL3, CCL4, and CXCL12." (PMID 38281962, 2024).
melanoma (9 papers, 2012 to 2025). A malignant, usually aggressive tumor composed of atypical, neoplastic melanocytes. "For example, folate receptor beta (FRβ)-specific CAR-T cells cause depletion of FRβ positive M2 cells in colon adenocarcinoma and melanoma." (PMID 36717905, 2023). "CXCL9, CXCL10, PD-L1, CD86, IL-10, TREM2, GPNMB, IL-4l1 and FOLR2 markers showed widespread expression by most melanoma TAMs, with no definition of a particular macrophage subset, and regardless of whether the tumor was metastasizing or not." (PMID 40406129, 2025).
Arthritis (8 papers, 2011 to 2022). Inflammation of a joint. "Folate receptor beta has been described to be associated with inflammatory disorders such as arthritis." (PMID 25971554, 2015). "Except for arthritis, ovarian TAMs also express a high level of folate receptor-2 (FOLR2), which can be selectively targeted using G5-methotrexate (act as both a ligand and a toxin) dendrimer NPs for cancer treatment." (PMID 35625939, 2022). "Clinical development programs employing monoclonal antibodies specific for either folate receptor alpha in certain cancers of epithelial origin, including EOC, and folate receptor beta in inflammatory disorders such as arthritis, are underway." (PMID 25971554, 2015).
atherosclerosis (8 papers, 2012 to 2026). A disease characterized by the build-up of fatty material and calcium deposition in the arterial wall resulting in partial or complete occlusion of the arterial lumen. "Next, we explored the potential of folate and glutamine as PET tracers, leveraging high expression of folate receptor (Folr2) and solute carrier family 7 member 7 (Slc7a7), respectively, in atherosclerosis-associated macrophages." (PMID 41206594, 2025).
hepatocellular carcinoma (8 papers, 2022 to 2025). A malignant tumor that arises from hepatocytes. "For example, FOLR2+ macrophages in human breast tumors interact with CD8+ T cells and promote anti-tumor immunity; in contrast, in hepatocellular carcinoma, FOLR2+ macrophages participate in immunosuppressive interactions with Treg cells." (PMID 38545103, 2024). "In human hepatocellular carcinoma, the overexpression of CD68 and CD163 in FOLR2+ TAMs have been associated with a worse prognosis." (PMID 38068740, 2023). "Previous study has found that three groups of cancer embryonic cells, including POSTN+ CAF, FOLR2+ TAM, and PLVAP+ EC, have close cellular communication connections in hepatocellular carcinoma." (PMID 39524442, 2024).
glioma (7 papers, 2011 to 2024). A benign or malignant brain and spinal cord tumor that arises from glial cells (astrocytes, oligodendrocytes, ependymal cells). "The genes analyzed included HLA‐DQA1, HLA‐DQB1, HLA‐DMB, LY86, MS4A7, FOLR2, and MS4A4A in glioma patients." (PMID 38997808, 2024).
lung adenocarcinoma (6 papers, 2018 to 2024). A carcinoma that arises from the lung and is characterized by the presence of malignant glandular epithelial cells. "Using immunohistochemistry, the expression levels of PSMB6, HSPA9, DUT, CDK7, and PLK1 were found to be higher in lung adenocarcinoma tissues of patients, while the expression of FOLR2 was low, which was consistent with survival prediction." (PMID 34721732, 2021). "However, FOLR2+ TAMs are enriched in more malignant invasive lung adenocarcinomas and are likely involved in CD4+ T-cell recruitment." (PMID 39516356, 2024).
Obesity (6 papers, 2012 to 2025). Accumulation of substantial excess body fat. "We also observe previously identified obesity associated genes, such as Zfp69, Slc24a3, Qpctl, Atp10a, and Folr2." (PMID 22471599, 2012). "By flow cytometry and imaging, we show how obesity disrupts macrophage homeostasis as regulatory FOLR2+CD11c− cells are diminished while pro-inflammatory FOLR2CD11c+ macrophages are expanded." (PMID 40909804, 2025). "In obesity, the pancreatic macrophage landscape shifts to lower predominance of FOLR2+CD11c−macrophages and higher FOLR2−CD11c+macrophages which interact selectively with the TRM and inflamed exocrine epithelium." (PMID 40791478, 2025). "Thus, the pancreatic macrophage landscape shifts in obesity, with pro-inflammatory CD11c+ macrophages displacing fetal-derived immunoregulatory FOLR2+ macrophages." (PMID 40909804, 2025). "In addition, the upregulation of FOLR2 may contribute to an unfavorable vascular phenotypic switch induced by obesity." (PMID 38396970, 2024). "Upregulated expression of Retnla/Fizz1 and Folr2 genes in HFD macrophages suggests that HFD-induced obesity stimulates the generation and/or recruiting of M2 macrophages in mammary glands, which is a sign of immunosuppression." (PMID 32785175, 2020). "Additionally, we found that Folr2+macrophages act similarly in both visceral and subcutaneous adipose tissue, but the interaction between Folr2+ macrophages and adipocytes is not strong and is reduced by obesity." (PMID 37454080, 2023).
COVID-19 (5 papers, 2020 to 2025). A disease caused by infection with severe acute respiratory syndrome coronavirus 2. "Other surface molecules associated with druggable targets were also identified; FOLR2 was another candidate imaging target for the severe COVID-19 group." (PMID 34239034, 2021). "C1Qhi macrophage representation in NALT remained stable in health, acute and convalescent COVID-19, but FOLR2+ macrophages significantly increased in convalescent COVID-19." (PMID 39890933, 2025). "In the present study, we found that human NALT contains a dense network of macrophages, including a FOLR2+ population, which expanded in convalescent COVID-19, expressing IL18, and pro-repair molecules, including type VI collagen." (PMID 39890933, 2025). "Several proteins related to innate immune cell activation are upregulated in patients with COVID-19, such as FOLR2, anti-inflammatory macrophage markers, and CCL26." (PMID 37047248, 2023). "Regarding alleged imaging markers, SLC2A3 was abundant in macrophage subtypes enriched in severe COVID-19 patients, and we identified SLC3A2, SLC2A3, and FOLR2 as candidate molecules as imaging targets." (PMID 34239034, 2021). "Among the significantly up- or down-regulated proteins in COVID-19 patient urine, metallothionein-1G, lipoprotein lipase, β2M, PRKACA, FOLR2, and APOA4, showed significant changes compared to both healthy controls and non-COVID-19 pneumonia cases." (PMID 33203833, 2020). "SLC3A2 and SLC2A3 in the M01 cluster and FOLR2 in the M03 cluster were identified in results from both methods, indicating that [18F]FDG and [18F]-labeled folic acid derivatives may be useful for imaging severe COVID-19." (PMID 34239034, 2021).